LEP (leptin)
Diseases named in the same sentence as LEP in open-access papers (continued):
Sharing a sentence is not in itself a finding about the gene and the disease.
lymph node metastasis (25 papers, 2010 to 2025). "Cutaneous melanoma patients who have relatively high serum leptin expression levels are at a significant risk of sentinel lymph node metastasis." (PMID 33804101, 2021). "Another clinical study revealed that cutaneous melanoma patients with higher leptin levels in serum samples also had a high risk of sentinel lymph node metastasis." (PMID 33799880, 2021). "A correlation has also been established between leptin concentrations and lymphatic vessel infiltration with lymph node metastases, which is also consistent with our findings above." (PMID 32570721, 2020). "For group G, lymph node metastasis positive cases displayed higher leptin level; and all the individual study reported positive results." (PMID 23826274, 2013). "In renal cell carcinomas leptin and leptin receptor expression was well correlated with progression-free survival, venous invasion and lymph node metastasis." (PMID 21338489, 2011). "However, the positive rate of LEP expression in patients with lymph node metastasis was 91.8%, which was significantly higher than 67.5% in patients without lymph node metastasis (P = 0.002)." (PMID 36941557, 2023). "Interestingly, further analysis found that tissue leptin protein levels were statistically different between the lymph node metastases group and the non-lymph node metastases group (OR=3.83, 95%CI=2.18–6.72, P<0.001)." (PMID 28160559, 2017). "It was recently shown that leptin, which uses ROCK as a critical signal mediator, induces migration and invasion of human pancreatic cells via MMP13 up‐regulation, while increased MMP13 expression in patients was associated with lymph node metastasis and pathological stage." (PMID 28031255, 2017). "We demonstrated that leptin, resistin, and visfatin might increase the risk of onset and lymph node metastasis of postmenopausal BC cases only and not in premenopausal BC group." (PMID 25838618, 2015). "The LEP and LEPR expression were significantly correlated with lymph node metastasis and Ki-67 expression, respectively." (PMID 36941557, 2023). "Our results also show that leptin and TNF-α levels are positively correlated with lymph node metastasis status." (PMID 29088874, 2017). "Accordingly, each expression of leptin, pSTAT3, ERK, pAkt, and HIF-1alpha showed a correlation with the early cancer stage (TNM stage based on tumor invasion depth-lymph node metastasis-distant metastasis) (P < 0.05, respectively)." (PMID 26147886, 2015). "The LEP expression in patients with lymph node metastases was significantly higher than that in patients without lymph nodes metastases (P = 0.002)." (PMID 36941557, 2023). "Further more, for the postmenopausal patients or triple negative patients and lymph node metastasis patients, LEP-positive group had worse prognosis." (PMID 36941557, 2023). "Neither leptin nor OBR expression levels were associated with other parameters, including age, body weight, postmenopausal state, multifocality and lymph node metastasis." (PMID 23425972, 2013). "Neither leptin nor OBR expression was associated with other parameters, including age, body weight, postmenopausal state, multifocality or lymph node metastasis." (PMID 23425972, 2013). "We found a significant correlation between HIF-1α and leptin expression in primary tumors and lymph node metastases in patients who did not receive preoperative chemotherapy." (PMID 20569445, 2010). "In addition, leptin levels were also significantly higher in lymph node metastasis (LNM) positive cases than in LNM negative cases, and considerably higher between post-menopausal and pre-menopausal women." (PMID 36900364, 2023). "Present study found that LEPR expression did not significantly correlated with lymph node metastases (p = 0.66), but the expression rate of LEP in patients with lymph node metastasis was significantly higher than that of patients without lymph node metastasis (p = 0.002)." (PMID 36941557, 2023).
lymph node metastasis (continued). "In addition, the BC cases with lymph node metastases indicated significantly higher serum leptin levels than those with no lymph node metastases (SMD = 0.53, 95% CI = 0.10–0.95, P = .015)." (PMID 30702563, 2019). "Leptin and TNF-α levels were also significantly higher in lymph node metastasis (LNM) positive cases than in LNM negative cases, with a pooled SMD of 0.80 (95% CI, 0.45, 1.14; P < 0.00001) and 0.63 (95% CI, 0.30, 0.96; P = 0.0002) respectively." (PMID 29088874, 2017). "Expression of leptin, pSTAT3, ERK, pAkt and HIF-1 alpha were correlated with the absence of lymph node metastasis, while leptin-receptor positivity was related with lymph node metastasis (P < 0.05, respectively)." (PMID 26147886, 2015).
periodontal disease (25 papers, 2010 to 2025). "The association between leptin and periodontal disease has been demonstrated in both clinical observations and animal model studies." (PMID 41154857, 2025). "Periodontal disease status was evaluated; serum levels of leptin, adiponectin, and CRP were determined by enzyme-linked immunosorbent assay at baseline, as well as at 3 and 6 months after NSPT." (PMID 33603787, 2021). "This study demonstrated that elevated salivary leptin and calprotectin levels, along with decreased adiponectin levels, may be associated with the severity of periodontal disease." (PMID 41300847, 2025). "Leptin level changes are also associated with overweight and periodontal disease." (PMID 39699988, 2024). "Therefore, we speculate that a high concentration of leptin and visfatin in obese patients may increase the risk of periodontal disease." (PMID 37231396, 2023). "We hope that despite these limitations, the results of our study will contribute to a better understanding of the role of leptin in periodontal disease." (PMID 41154857, 2025). "Previous research has indicated a link between leptin and the development of periodontal disease, although findings remain inconclusive." (PMID 41154857, 2025). "Our main findings indicate that salivary leptin levels increase with disease severity, supporting the role of this adipokine in the inflammatory cascade of periodontal disease." (PMID 41300847, 2025). "Further research is therefore needed to comprehensively determine leptin’s role in the development of periodontal disease." (PMID 41154857, 2025). "Collectively, these findings indicate that calprotectin and adiponectin exert independent influences on periodontal disease progression, whereas leptin appears to have a more limited role in multiple contexts." (PMID 41300847, 2025). "A bidirectional relationship between periodontal disease pathogenesis and serum leptin levels has been demonstrated." (PMID 41300847, 2025). "Periodontal diseases can affect overall health by altering the levels of adipokines (IL-1β, leptin, resistin, and adiponectin) in the serum, saliva, and GCF of obese female patients." (PMID 36767065, 2023). "Previous several studies have demonstrated the role of GCF leptin activity in development of periodontal disease and itspresence in marginally inflamed and in healthy gingivae." (PMID 37168792, 2022). "It is reported that leptin (expressed from adipocytes) shows an inverse relation with periodontal inflammation demonstrating a protective role in periodontal disease." (PMID 27795608, 2016). "The present findings with respect to subjects without T2DM are consistent with earlier reports of higher levels of leptin in periodontally healthy subjects than in those with periodontal disease." (PMID 25993052, 2015). "Because of this, several studies have assessed the possible implication of leptin in periodontal disease." (PMID 25662559, 2015). "In this context, it is noteworthy that detection of high local leptin levels in T2DM patients with periodontal disease is regarded as one of the indicators of cardiovascular complications." (PMID 25993052, 2015). "Leptin, adiponectin, and calprotectin levels have been hypothesized to vary across different stages of periodontal disease." (PMID 41300847, 2025). "The aim of this study was to examine the effect of leptin on periodontal ligament cells and their secretion of selected pro-inflammatory mediators that may contribute to the pathogenesis of periodontal disease." (PMID 41154857, 2025). "The aim of this study was to investigate the effect of leptin on periodontal ligament cells and their secretion of selected pro-inflammatory mediators that may contribute to the pathogenesis of periodontal disease." (PMID 41154857, 2025). "In both pulp and periapical infections as well as periodontal disease, leptin levels are increased." (PMID 33020413, 2020).
periodontal disease (continued). "In further research, other systemic markers that might be more specific to periodontal disease such as fibrinogen, leptin, white blood cell count, and interleukin-6 should be considered." (PMID 26346216, 2015). "In addition, Leptin has been shown to regulate bone formation; consequently, there are several studies have assessed the correlation between Leptin and periodontal disease." (PMID 23130043, 2010). "The plasma levels of leptin have been reported to increase as periodontal disease progressed." (PMID 20607056, 2010). "In our study, we examined the effect of leptin on periodontal ligament cells, which are an important component of the dental ligament and may also be a source of cytokines involved in the development of periodontal disease." (PMID 41154857, 2025). "In the future, targeting leptin/NLRP3 signaling may be applied to elucidate the mechanisms of the alveolar bone and periodontal diseases." (PMID 36979821, 2023). "Leptin which is found in the Gingival Crevicular Fluid (GCF), has higher concentrations in subjects with healthygingival tissues as compared to subjects with periodontal disease." (PMID 37168792, 2022). "Further, the results of Karthikeyan and Pradeep showed a strong negative correlation between the GCF leptin concentration and periodontal disease progression." (PMID 20607056, 2010).
dyslipidaemia (24 papers, 2011 to 2025). "The novelty of our study lies in the comparison of four markers of cardiovascular risk: dyslipidaemia [lp(a)], insulin reistance (leptin), inflammation (hs-CRP) and matrix remodelling (PAPP-A), as possible predictors of plaque instability." (PMID 22836155, 2012). "Sleep restriction is associated with hormone imbalance; it reduces leptin (an appetite suppressant) and elevates ghrelin levels (an appetite stimulant), 33 which may contribute to increased body weight and lead to dyslipidaemia." (PMID 29084786, 2017). "Mutations in ADCY3 in mice cause impaired insulin sensitivity and dyslipidaemia and mice with ADCY3 knockout show increased fat mass, hyperphagia, depression-like phenotypes, and leptin resistance." (PMID 37368776, 2023). "Dyslipidaemia is characterised by a high FFA level; an imbalance of leptin, resistin, and adiponectin; and a deficiency of ghrelin in the acute and early recovery periods of MI." (PMID 24433403, 2014). "The results of our investigation have clearly highlighted the strong association with ADRB3 polymorphism, where the mutant Arg allele in ADRB3, significantly associates with a greater body weight and higher BMI, elevated leptin and dyslipidaemias both in heterozygous and homozygous." (PMID 29587766, 2018). "Dyslipidaemia was noted in many cases, with elevated fasting triglycerides of between 332 and 927 mg/dL (3.75–10.5 mmol/L) (normal range < 150 mg/dL or < 1.7 mmol/L) but seemingly normal leptin levels of 3.5–7.4 ng/mL (normal range for females 8.8 + SEM 2.10 ng/mL)." (PMID 32388841, 2020).
esophageal adenocarcinoma (24 papers, 2007 to 2026). A malignant tumor with glandular differentiation arising predominantly from Barrett mucosa in the lower third of the esophagus. "High leptin levels are associated with an increased risk of esophageal adenocarcinoma in obese individuals." (PMID 38255203, 2024). "In esophageal adenocarcinoma, increased adipocyte diameter in the peritumoral adipose tissue expresses higher levels of leptin and is also associated with increased levels of CD31." (PMID 37686525, 2023). "A case-control study found that elevated blood leptin levels are strongly associated with an increased risk of Barrett’s esophagus." (PMID 37025412, 2023). "A systematic review showed that increased serum levels of leptin are associated with an increased risk of Barrett’s esophagus." (PMID 33167521, 2020). "In patients with esophageal adenocarcinoma, an increase in adipocyte size was directly associated with leptin expression, angiogenesis, and lymphangiogenesis." (PMID 33334030, 2020). "High leptin levels and low levels of high molecular weight adipnectin have been associated with an increased risk for progression from Barrett’s esophagus to EAC after adjustment for relevant other risk factors, including BMI." (PMID 24548688, 2014). "Previous studies have found that higher circulating levels of certain metabolic and inflammatory biomarkers, including leptin, glucose, insulin, C-reactive protein, interleukin 6, and soluble tumor necrosis factor receptor 2, are associated with an increased risk of esophageal adenocarcinoma." (PMID 40917762, 2025). "Leptin, secreted by peritumoral adipocytes, may be linked to cancer progression in esophageal adenocarcinomas." (PMID 38255203, 2024). "The reduction in leptin concentrations following the exercise intervention in the present study (-21.2% in exercise group vs. +4.6% in control group) is therefore likely to be important in reducing risk of oesophageal adenocarcinoma." (PMID 25706622, 2015). "In patients with esophageal adenocarcinoma, an increase in adipocyte size is observed together with angiogenesis/lymphangiogenesis and increased leptin expression." (PMID 40136652, 2025). "In esophageal adenocarcinoma cell lines, leptin promotes cell proliferation and activates JAK2, ERK or Akt signaling pathways leading to cancer progression." (PMID 40136652, 2025). "It has been demonstrated that in Barrett-derived esophageal adenocarcinoma cells, leptin promotes cell proliferation and inhibits apoptosis." (PMID 39512967, 2024). "The protein kinase Akt is essential to the growth-promoting and anti-apoptotic effects of leptin in oesophageal adenocarcinoma cells." (PMID 33582946, 2021). "Leptin stimulates the growth of cancer cells, including esophageal adenocarcinoma cell lines, through the activation of janus kinase 2 (JAK2) and p38 mitogen-activated protein kinase (p38MAPK) pathways." (PMID 33513939, 2021). "Leptin is a growth factor for several cell types, including Barrett’s cells and oesophageal adenocarcinoma cells." (PMID 33582946, 2021). "In Barrett’s esophageal adenocarcinoma, leptin appeared to increase cell proliferation and abolish apoptosis via the transactivation of the epidermal growth factor receptor and JNK activation." (PMID 33804101, 2021). "An increased level of leptin was associated with an increased risk for esophageal adenocarcinoma, whereas an increased level of HMW adiponectin was inversely associated with esophageal adenocarcinoma." (PMID 33167521, 2020). "In Barrett's esophageal adenocarcinoma cells, leptin has been reported to stimulate cell proliferation and impede apoptosis via a complex cascade of reactions." (PMID 27185268, 2016). "Beales and Ogunwobi demonstrated that the P4244 MAP kinase inhibitor PD98059 enhanced the activity of leptin-mediated esophageal adenocarcinoma cell apoptosis." (PMID 25373392, 2015).
esophageal adenocarcinoma (continued). "In vitro, leptin has been shown to elicit mitogenic, angiogenic and anti-apoptotic effects when administered to oesophageal adenocarcinoma cell lines, enhancing cellular proliferation." (PMID 25706622, 2015). "Leptin, a hormone secreted by adipocytes and increased in the obese state, has been postulated in the development of oesophageal adenocarcinoma as well as other cancers." (PMID 25706622, 2015). "Previously, leptin has been shown to induce PGE2 production in OE33 Barret's esophageal adenocarcinoma (EAC) cell-line and in murine J774A.1 macrophages." (PMID 19688109, 2009). "Driving GERD pathogenesis via adipocyte cytokines: Studies demonstrate a significant association between low adiponectin levels and high incidence rates of erosive esophagitis and Barrett’s esophagus, while serum leptin levels correlate positively with GERD onset." (PMID 41384250, 2025). "Recently, elevated leptin concentrations have been associated with progression from Barrett’s oesophagus to oesophageal adenocarcinoma in men independent of adiposity." (PMID 25706622, 2015). "In Barrett’s esophageal adenocarcinoma cell lines BIC-1 and SEG-1, leptin has been shown to promote cell proliferation." (PMID 33334030, 2020). "The multi-biomarker score derived from multiple parameters, including leptin levels and GERD frequency and duration, can identify patients with Barrett’s esophagus." (PMID 33167521, 2020). "Moreover, leptin levels were found to be positively associated with Barrett’s esophagus; this association was stronger in men with GERD than in women with GERD, and serum leptin levels might be associated with an increased risk of Barrett’s esophagus among men but not women." (PMID 33167521, 2020). "With nodal metastasis, interestingly, leptin increased the mRNA levels of two key regulator genes of EMT, α-SMA and E-cadherin, in OE33 esophageal adenocarcinoma cells." (PMID 33334030, 2020). "Exogenous leptin significantly increased proliferation in both OE33 and OE19 oesophageal adenocarcinoma cell lines." (PMID 17559672, 2007). "Amazingly, there may be another link in the network; leptin has been shown to increase the gene expression of HB-EGF and extracellular release of HB-EGF in human oesophageal adenocarcinoma cells and this was blocked by MMP9 inhibitor." (PMID 32906753, 2020). "The finding that patients with Barrett’s esophagus had higher fundic leptin levels than individuals with a normal esophagus indicates that ObR expression on esophageal epithelial cells provides a pathway for leptin-mediated signal transduction." (PMID 33167521, 2020). "In esophageal adenocarcinoma (EAC), leptin produced by peritumoral adipose tissue with increased cell diameter upregulates expression of EMT markers such as alpha-smooth muscle actin (α-SMA) and E-cadherin and thus may promote extension and penetration by cancer cells into neighboring tissues." (PMID 37686525, 2023).